CHD3 (chromodomain helicase DNA binding protein 3)
Diseases named in the same sentence as CHD3 in open-access papers (continued):
Sharing a sentence is not in itself a finding about the gene and the disease.
prostate carcinoma (1 paper, 2017). A carcinoma that arises from epithelial cells of the prostate gland. "Strikingly, homozygous deletions of CHD1 and CHD3 were found in 10.2% and 6.7% of prostate cancers, respectively." (PMID 28649742, 2017). "Strikingly, prostate cancer had a dramatically higher frequency of homozygous deletions of CHD1 and CHD3, in 10.2% and 6.7% of cases, respectively." (PMID 28649742, 2017).
Sepsis (1 paper, 2025). Sepsis is defined as life-threatening organ dysfunction caused by a dysregulated host response to infection. "A total of six hub genes (RORA, L3MBTL2, PHC1, RPA1, CHD3, and RANGAP1) associated with SUMOylation was identified in sepsis in the current study." (PMID 40274894, 2025). "Aflatoxin B1 was identified as a prospective therapeutic agent for sepsis based on CHD3, L3MBTL2, PHC1, RANGAP1, and RORA." (PMID 40274894, 2025). "This study shows that hub genes (RORA, L3MBTL2, PHC1, RPA1, CHD3, and RANGAP1) may distinguish controls and diseases to facilitate diagnosis of sepsis." (PMID 40274894, 2025).
type 1 diabetes (1 paper, 2025). "Whether interactions between CHD3, CHD4 with PDX1 are compromised in other β-cell stress conditions, for example, during type 1 diabetes progression, remains to be established." (PMID 41282155, 2025).
tumor (10 papers, 2016 to 2025). "The most strongly elevated cadherin after the WNT/β-catenin pulse, CDH3, was reported to correlate with the loss of an epithelial phenotype of tumor cells upon gaining the ability to migrate and invade other tissues, while CHD3 suppression apparently reversed this phenotype." (PMID 33195222, 2020). "These 19 de novo variants were present in non-coding regions including those of tumor associated genes ATR, RPS6KA2, IRF3, and CHD3 22–26." (PMID 34011996, 2021). "CHD3 is a chromatin remodeler related to CHD4, which is implicated as a tumor suppressor in several female malignancies." (PMID 34142659, 2021). "In addition to multiple single mutation events, we located two parallel single mutations (CHD3 and PLD2), which evolved independently in adenomatous polyps and in tumour cells." (PMID 36451239, 2022). "Among 17 identified genes, CHD3 was considered a potential tumor suppressor." (PMID 28649742, 2017). "Additionally, CHD3 levels negatively correlated with tumor grade, and PCGF2 and PCGF3 levels positively correlated with ER+ status." (PMID 27863398, 2016). "In contrast to CHD3 and CHD5, which most likely function as tumor suppressors, the role of CHD4 in various tumors appears to be quite complex." (PMID 28055972, 2017).
cancer (7 papers, 2017 to 2025). A tumor composed of atypical neoplastic, often pleomorphic cells that invade other tissues. "We found that CHD6 and CHD7 were most commonly gained/amplified or mutated, whereas CHD1 and CHD3 were most deleted in a spectrum of human cancers." (PMID 28649742, 2017). "We found that CHD6 and CHD7 were the most commonly gained/amplified or mutated, whereas CHD1 and CHD3 were the most deleted CHDs in a spectrum of human cancers." (PMID 28649742, 2017). "In summary, among nine CHD genes, CHD6 and CHD7 had the highest frequency of genetic gain/amplification, whereas CHD1 and CHD3 were most commonly deleted in a spectrum of human cancers." (PMID 28649742, 2017). "Among nine CHDs, CHD1 and CHD3 were most commonly deleted in a spectrum of human cancers." (PMID 28649742, 2017). "While expression of ACTA2 – a marker expressed by both myoepithelial cells and cancer-associated fibroblasts (CAFs) – significantly increased in CAS compared to normal stroma, expression of TP63, CHD3, MYH11, SERPINB5 and MME did not increase." (PMID 37391533, 2023).
neurodevelopmental disorder (7 papers, 2018 to 2025). A behavioral and cognitive disorder with onset during the developmental period that involves impaired or aberrant development of intellectual, motor, or social functions. "Eising found CHD3 gene mutations in a group of patients with severe language and neurodevelopmental disorders." (PMID 40527848, 2025). "Developmental processes regulated by NuRD and some subunits (including CHD3) have been linked to hereditary neurodevelopmental disorders in humans." (PMID 39050258, 2024). "This study utilized C. elegans to model one of the clinical variants of the NuRD subunit CHD-3, specifically the L915F mutation in neurodevelopmental disorders." (PMID 37938928, 2024). "Here, the authors identify missense variants in CHD3 that disturb its chromatin remodeling activities and cause a neurodevelopmental disorder with macrocephaly and speech and language impairment." (PMID 30397230, 2018). "Taken together, our data demonstrate that de novo missense mutations in CHD3 disturb chromatin remodeling activities of the encoded protein, thereby causing a neurodevelopmental disorder." (PMID 30397230, 2018). "Finally, CHD5 mutations have recently been identified as causing a neurodevelopmental disorder that is clinically very similar to those associated with CHD3 and CHD4 mutations." (PMID 40004235, 2025). "Our findings are consistent with the identification of multiple de novo mutations disrupting the same functional domain of CHD3 in other patients with neurodevelopmental disorders involving speech and language problems (L. Snijders Blok, personal communication)." (PMID 29463886, 2019). "In this study, we show that de novo CHD3 mutations cause a neurodevelopmental disorder." (PMID 30397230, 2018). "A significant number of these genes (CHD3, SETD1A, KAT6A, SETBP1, TNRC6B, ZFHX4, ARID1A and TRIO) have been associated with neurodevelopmental disorders with or without speech problems." (PMID 29463886, 2019). "The CHD3 gene may be a new gene for IS, and the possibility of carrying a CHD3 gene variation should also be considered in children who present only with neurodevelopmental disorder without seizures." (PMID 40527848, 2025).
infection (1 paper, 2015). The state of being infected such as from the introduction of a foreign agent such as serum, vaccine, antigenic substance or organism. "Though different from the punctate distribution of NLS–cCHD3, the endogenous CHD3 still predominantly co-translocated with NS2 in the nucleus in the early stage of the infection." (PMID 25213355, 2015). "CHD3 could be immunoprecipited with mouse anti-Flag monoclonal antibody with WD-Flag-NS2 infection, demonstrating that NS2 interacts with CHD3 in vivo." (PMID 25213355, 2015).
CHD3 also shares sentences with these, for which no sentence is quoted: dermatomyositis (5 papers); myositis (5); developmental delay (4); Myalgia (3); myopathy (3); autism (2); connective tissue disease (2); acute lymphoblastic leukemia (1); adrenal hypoplasia (1); anemia (1); autosomal dominant disease (1); bladder cancer (1); childhood apraxia of speech (1); cleft lip (1); cleft palate (1); depression (1); diffuse large B-cell lymphoma (1); endometrial cancer (1); familial amyloidosis (1); fibromyalgia (1); follicular lymphoma (1); genetic disorder (1); ischemia (1); lung disease (1); lung small-cell carcinoma (1); Macrocephaly (1); neurological disorders (1); neuropathy (1); oral cancer (1); overlap syndrome (1).
A further 11 diseases each share a sentence with CHD3 in 1 paper.